MYC (MYC proto-oncogene, bHLH transcription factor)
Diseases named in the same sentence as MYC in open-access papers (continued):
Sharing a sentence is not in itself a finding about the gene and the disease.
hematological malignancies (continued). "Consequently, plasma c-MYC ratio > 9.42 in the presence of other risk factors for hematological malignancies (such as presence of the disease in family, hazardous occupational exposure, etc) is a red flag for possibility of developing hematological malignancies." (PMID 38223598, 2023). "In this study, we observed that c-MYC expression (plasma) level in hematological malignancies was significantly higher (8.8 ± 1.1; Mean ± SE) (p<0.05) than that of the apparently healthy control subjects (4.5 ± 0.5; Mean ± SE)." (PMID 38223598, 2023). "Plasma c-MYC was higher in subject with hematological malignancies (8.8 ± 1.1) when compared with apparently healthy controls (4.5 ± 0.5)." (PMID 38223598, 2023). "The subjects with hematological malignancies were followed up for 3 years in order to determine the prognostic relevance of c-MYC expression." (PMID 38223598, 2023). "This study is aimed at comparing c-MYC expression in hematological malignancies and apparently healthy subjects as well as assess its diagnostic and prognostic role." (PMID 38223598, 2023). "The subjects with hematological malignancies were divided into two subgroups (high c-MYC and low c-MYC) using the cut-off value (9.42) generated via ROC curve analysis." (PMID 38223598, 2023). "In this study, we found significantly elevated expression of plasma c-MYC gene in hematological malignancies when compared with those of apparently healthy controls." (PMID 38223598, 2023). "In hematological malignancies, genetic and epigenetic alterations of the MYC gene increase the tumorigenic potential of MYC, resulting in the transcriptional upregulation of MYC target genes." (PMID 35216159, 2022). "In the subsequent sections, we elaborate on the role of MYC in different types of hematological malignancies." (PMID 34372899, 2021). "Recently, fadraciclib, a potent inhibitor of CDK9 showed an ability to repress MYC and is currently in early-phase clinical trials for solid tumors and hematologic malignancies." (PMID 34638300, 2021). "Genes for several non-coding RNAs including both miRNA and lncRNAs are located in the vicinity of the MYC gene locus where they play important roles in the regulation of MYC in both normal cells and in hematological malignancies." (PMID 33134177, 2020). "For instance, as described in greater detail below, the combination of HDAC and PI3K inhibition impairs MYC-dependent growth in hematological malignancies." (PMID 32102485, 2020). "MYC-induced transcriptional pathways were also found to be reactivated after treatment with HDACi’s in hematologic malignancies." (PMID 32210076, 2020). "Aberrant expression of MYC protein in these hematological malignancies results in an uncontrolled rate of proliferation and, thereby, a blockade of the differentiation process." (PMID 32102485, 2020). "CEBPA and c-MYC genes belong to TF and play an essential role in hematologic malignancies development." (PMID 33170359, 2020). "For instance, class I/IIb-selective HDACi purinostat has demonstrated a direct effect on MYC downregulation, while other selective drugs (mocetinostat, entinostat) are already undergoing clinical trials for diverse hematological malignancies." (PMID 32102485, 2020). "FBXW7 is the most important E3 ligase for MYC ubiquitination and proteasomal degradation in hematologic malignancies, which is dependent on T58 phosphorylation of MYC41,48." (PMID 33298911, 2020). "Relevant for this review is the lncRNA/miRNA/MYC axis, because it is involved in hematological malignancies." (PMID 33134177, 2020). "It has been now appreciated that super-enhancers related to MYC are frequently hyper-activated in a wide range of hematologic malignancies." (PMID 31311566, 2019). "For instance, in hematological malignancies, c-MYC is deregulated by different mechanisms, including chromosome rearrangements, amplification, mutations and also epigenetic mechanisms, such as aberrant microRNA regulation." (PMID 26497210, 2016).
hematological malignancies (continued). "In hematological malignancies c-MYC regulation is lost and often occurs when it is aberrantly expressed via amplification or genetic alteration, consequently leading to events ranging from promotion of excessive proliferation of altered cells to inhibition of apoptosis 8,15,16." (PMID 38223598, 2023). "c-MYC is a well-documented oncogene in hematological malignancies." (PMID 37047788, 2023). "The conserved MYC homology box 1 (MB1) within the transactivation domain contains a transiently structured proline-rich sequence where missense mutations frequently occur in BL and other hematological malignancies." (PMID 34885204, 2021). "In principle, SK2 inhibitors like ABC294640 may be a potential therapeutic approach toward down-regulating MYC expression in different hematological malignancies." (PMID 34372899, 2021). "Ibrutinib, a BCR-signaling inhibitor which is under clinical trials for several hematologic malignancies could be a potential compound for inhibition of MYC induced proliferation in B-cell malignancies [NCT02303392]." (PMID 34372899, 2021). "Further, we also discuss potential inhibitors of MYC that could be beneficial for treating hematologic malignancies." (PMID 34372899, 2021). "Prior work, primarily in hematologic malignancies, showing that genes whose enhancers have high levels of H3K27ac (e.g. MYC) tend to be exquisitely sensitive to BET inhibition provides additional support to this hypothesis." (PMID 28891793, 2017). "Since bromodomain and extraterminal (BET) proteins (such as BRD2 and BRD4) regulate MYC‐dependent transcription, various potent and selective small‐molecule inhibitors of these proteins have been developed and clinical trials are currently ongoing in hematological malignancies." (PMID 32623836, 2020). "Furthermore, previous studies showed that bromodomain and extraterminal domain inhibitor (BETi) had potent antagonism to MYC transcriptional activity and protein expression and exhibited antitumor activity in various hematological malignancies, including DLBCL." (PMID 31403034, 2019). "Subgroup analysis showed the strongest effects in hematological malignancies (g = 0.85), particularly in studies targeting oncogenes such as KRAS, MYC, and PIK3CA." (PMID 41517680, 2026). "In another report of patients with hematologic malignancies with dmin, molecular genetic testing and FISH analysis revealed MYC (8q24) amplification." (PMID 40932956, 2025). "In hematological malignancies, SMARCA4 promotes transcription factor binding to lineage-specific MYC enhancer elements, driving long-range chromatin looping interactions with the MYC promoter to favor oncogenic gene expression." (PMID 38390898, 2024). "Preclinical and clinical studies have demonstrated the efficacy of BET inhibition in several hematological malignancies 29, 30, in which inhibition of BRD4 leads to downregulation of MYC expression 31, a master regulator of cell survival and proliferation." (PMID 38169595, 2024). "DCR-MYC, an EnCore lipid nanoparticle containing siRNA against MYC, was used in clinical trials to treat solid tumors [NCT02314052] and hematological malignancies[NCT02110563]." (PMID 34372899, 2021). "The oral iBET Birabresib (OTX015, also known as MK-8628) has been shown to reduce MYC expression and increase HEXIM1 in various types of hematological malignancies." (PMID 34372899, 2021). "Compared with the patients with other hematological diseases, the patient had higher levels of LYL1, NOTCH1, PAX5, MYC, and E2B, all of which contribute to the development of T and B cells." (PMID 33126303, 2020). "Since PVT1 also acts as a cis regulatory lncRNA, the interaction between MYC and PVT1 in different hematological malignancies has to take place via a positive feedback loop." (PMID 33134177, 2020).
hematological malignancies (continued). "c-MYC is the first oncogene that has been described to be regulated by BRD4, both in solid tumors and hematological malignancies, providing a rationale for the development of pharmacological inhibitors of BET proteins." (PMID 30841549, 2019). "In hematological malignancies, OTX-015 has been shown to target, in addition to c-MYC, also the NFKB/TLR/JAK/STAT signaling and to synergize with everolimus in B-cells lymphoma in vitro and in vivo." (PMID 30841549, 2019). "MYC regulating factorsinclude BET family, MCL-1, BCR-signaling mediators, HDACs, PI3Kδ, DNA-PK, CDKs, kinases and G-quadraplex (Refer to “The role of MYC in hematopoiesis and hematological malignancies" section)." (PMID 34372899, 2021). "The proto-oncogene c-MYC (MYC) is a basic helix-loop-helix leucine zipper transcription factor conserved in metazoans that is hyperactivated in a wide variety of solid tumors and hematological malignancies." (PMID 33803184, 2021). "Due to their close proximity at the 8q24 locus, PVT1 and MYC are often considered tween players, and a positive interaction feedback loop has been demonstrated in solid tumors and in APL and MM, among hematological malignancies." (PMID 32228602, 2020). "All MYC+RUNX2-DKO mice died 1 month post-transplantation, whereas there were no lethal hematological malignancies in MYC+RUNX2-WT or DKO mice 6 months post-transplantation." (PMID 30971697, 2019). "Given that adapalene might be a novel potential c-MYC inhibitor that has not yet been reported as a therapy for hematological malignancies, we examined the cytotoxic effect of adapalene in MM, T-ALL, and PBMCs using the resazurin cell viability assay." (PMID 37627164, 2023). "Therefore, a link between c-MYC deregulation and EZH2 overexpression could be involved in the physiopathology of hematological malignancies." (PMID 26497210, 2016).
adenocarcinoma (86 papers, 2004 to 2026). A common cancer characterized by the presence of malignant glandular cells. "This study shows a significant association between adenocarcinomas with c-MYC expression and the presence of distant metastasis (p<0.05)." (PMID 33759958, 2021). "We identified frequent CNVs of the ATRX and RB1 genes in NENs and key driver mutations of the ARID1A, PIK3CA, CTNNB1, and MYC genes in nNENs, especially adenocarcinomas." (PMID 34422662, 2021). "In wild type KRAS/BRAF invasive adenocarcinomas with nuclear beta-catenin, increased c-MYC expression was associated with an up-regulation of SIRT1." (PMID 23045412, 2012). "The gene encoding c-MYC is located within chromosomal region 8q23–24.2, a region frequently amplified in adenocarcinomas of the oesophagus and gastro-oesophageal junction and that has been detected in Barrett's metaplasia." (PMID 18493233, 2008). "This case suggests a potential association with MYC-driven lineage plasticity, where a solid-type adenocarcinoma may undergo de-differentiation into an SCLC-like phenotype." (PMID 42239895, 2026). "IDC-P arises from the same ancestral clone as adenocarcinoma, but specific abnormalities, such as MYC amplification, occur earlier in BRCA2-mutant PCa." (PMID 39840193, 2024). "Adenocarcinoma is one of the most common pathologic types of PCa, and past studies have pointed to MYC as a major driver of prostate adenocarcinoma occurrence and progression (Surintrspanont, Zhou 2022)." (PMID 39470950, 2024). "Following adenocarcinoma identification, we evaluated activity levels of the MYC pathway and NME2 TR program in both neoadjuvant and adjuvant samples." (PMID 38191557, 2024). "In the CIS stage of Ad5-CC10-Cre-infected KP lungs, the portion of MYC+ cells was drastically reduced and continued to decrease during adenocarcinoma tumorigenesis." (PMID 38093367, 2023). "At 6 months of age, the MYC-expressing prostates have well-developed tumors of adenocarcinoma, which is reflected in the size of the prostates of the hiMYC mice compared to wt mice." (PMID 35228520, 2022). "CNA gain of EGRF was also more common in the mucinous MSS cohort compared to the adenocarcinoma NOS MSS cohort (38.5% vs. 0.0% p < 0.0001) as was CNA gain of MYC (61.5% vs. 0.0% p < 0.0001)." (PMID 32984045, 2020). "To further characterize columnar cells that are the hallmarks of advanced adenocarcinoma, we typed them for lineage and progenitor cell markers as in the case of the pre-malignant lesions in SpC-c-MYC single transgenic mice." (PMID 19551151, 2009). "Semi-quantitative analysis suggested that c-MYC expression in dysplastic Barrett's mucosa and adenocarcinoma tissue was significantly higher than in normal oesophageal and gastric mucosae." (PMID 18493233, 2008). "In the present study we found that, as compared to high grade PIN, the staining for Nkx3.1 protein actually increased substantially in pre-invasive cribriform PIN/CIS lesions and in early invasive adenocarcinomas, and these levels correlated inversely with levels of MYC expression." (PMID 20195545, 2010). "When cells are engineered to over-express MYC, BCL2 and activated AKT (ACB genes, for AKT, c-MYC and BCL2), they transform to adenocarcinoma." (PMID 39858043, 2025). "Amplification of MYC is frequently observed in transformed SCLC and prostate NE tumors, as well as in pre-transformed adenocarcinomas, indicating that MYC is a crucial factor in the early stages of transformation." (PMID 40507907, 2025).
adenocarcinoma (continued). "In the adenocarcinoma group, a moderate agreement between c-MYC and AXL was found using the Kappa coefficient of agreement, since it was seen 28 (71.8%) concordant cases (c-MYC+/AXL+ or c-MYC- /AXL-) and 11 (28.2%) discordant cases." (PMID 33759958, 2021). "Several of the identified mGISTIC regions harbored known or putative adenocarcinoma driver candidates, such as EGFR, MDM2, KRAS, MYC, TERT, MET, CCND1, NKX2-1/TITF1, CDK4, ERBB2, ID1, RB1, CDKN2A and PTEN." (PMID 24205279, 2013). "In Lo-MYC mice, the levels of MYC in the pre-invasive cribriform PIN/CIS lesions and in early adenocarcinoma lesions were decreased somewhat as compared to their precursor high grade PIN lesions." (PMID 20195545, 2010). "Further, we verify that the histopathological features of MYC driven mouse PIN and early adenocarcinoma are highly similar to their human counterparts, and have shown that Nkx3.1 mRNA and protein are negatively regulated in PIN lesions by MYC." (PMID 20195545, 2010). "Certainly, additional studies to determine why MYC is highly overexpressed in human PIN and adenocarcinoma lesions are warranted." (PMID 20195545, 2010). "The aims of this work were to characterise the expression of c-MYC, MAX and the MAD family in adenocarcinoma development and assess the effects of overexpression on cellular behaviour." (PMID 18493233, 2008). "Conversely, invasive adenocarcinomas negative for nuclear beta-catenin did not reveal any substantial c-MYC and SIRT1 staining (data not shown)." (PMID 23045412, 2012). "Progression to adenocarcinoma was accelerated in the MPAKT/Hi-MYC model with evidence of invasion in 8% of mice at 5–9 weeks, and in 67% mice at 16–20 weeks, compared respectively with 0% and 25% of Hi-MYC mice (sample size precluded statistical significance)." (PMID 21394210, 2011). "In order to address whether forced overexpression of MYC at levels much lower than those seen in Lo-MYC and Hi-MYC mice can also result in PIN and/or adenocarcinoma, we generated a new mouse strain that overexpresses human MYC in the prostate." (PMID 20195545, 2010). "To determine whether USP13 can alter the lineage characteristics of advanced lung tumors through MYC, we overexpressed USP13 in the murine adenocarcinoma KP primary cell line and human LUAD cell lines followed by immunoblotting for squamous markers, such as SOX2, p40, or CK5." (PMID 38093367, 2023). "Indeed, a detailed genomic analysis of chromosome 8q has been performed on gastroesophageal junction (GEJ) adenocarcinomas and this study revealed other genes (ANXA13MTSS1FAM84BC8orf17, and PTK2) except MYC involved in the 8q amplification and the pathology of GEJ adenocarcinomas." (PMID 22559327, 2012).
prostate (48 papers, 2008 to 2026). "The mutual exclusivity of HUWE1 mutation and MYC genomic amplification we observe in human CRC strongly implicates them as critical mediators of colorectal tumourigenic." (PMID 28003334, 2017). "MYC mRNA and protein levels were expectedly elevated in colorectal liver metastases compared to normal liver tissue." (PMID 37347737, 2023). "TMPRSS2-ERG fusion protein activates a transcriptional program that contributes to prostate oncogenesis through upregulation of the expression of some key genes including MYC, EZH2 and SOX9 and repression of NKX3 expression." (PMID 31366128, 2019). "Nearly all CRCs that were examined displayed dysregulation of MYC transcriptional targets because of the activation of MYC by activated WNT signaling and/or inactivation of the TGF-β pathway, indicating an important role for MYC in colorectal carcinogenesis." (PMID 29361689, 2018). "Herein, we aimed to extend those observations, assessing the putative role of MYC in miRNAs’ regulation, specifically of miR-27a-5p, in prostate carcinogenesis." (PMID 29415999, 2018). "Herein, we aimed to elucidate the role of regulatory network between MYC and miRNAs in prostate carcinogenesis." (PMID 29415999, 2018). "Deregulated expression of MYC is a driver of colorectal carcinogenesis, necessitating novelstrategies to inhibit MYC function." (PMID 25253726, 2014). "Inappropriate activation of c-Myc (MYC) gene expression by the Wnt/ß-catenin signaling pathway is required for colorectal carcinogenesis." (PMID 21533051, 2011). "This analysis revealed strong correlations between c-MYC and the prostate tumor suppressor Kruppel-like factor 6 (KLF6) gene." (PMID 18190704, 2008). "Deregulated expression of MYC is a driver of colorectal carcinogenesis, suggesting that decreasing MYC expression may have significant therapeutic value." (PMID 33078202, 2021). "In addition, genomic data modeling predicts a molecular mechanism linking germline c-MYC overexpression and prostate tumorigenesis." (PMID 18190704, 2008).